IL17A (interleukin 17A)
Diseases named in the same sentence as IL17A in open-access papers (continued):
Sharing a sentence is not in itself a finding about the gene and the disease.
psoriasis (continued). "Considering that almost all IL-17 cytokines (notably IL-17A, IL-17F, IL-17C, and IL-17E) have been shown to play some role in psoriasis pathogenesis, an approach based on receptor blockade, rather than cytokine inhibition, provides a consistent and valuable treatment strategy." (PMID 34201664, 2021). "Asthma and psoriasis can coexist and what they have in common is IL-17A." (PMID 34829740, 2021). "Th17 lymphocytes and their related cytokines are also considered to play crucial roles in psoriasis; however, neutrophils and mast cells are the major source of IL-17A in psoriatic skin lesions, substantiating the importance of neutrophils in the pathogenesis of psoriasis." (PMID 34565327, 2021). "As psoriasis develops, T cells and neutrophils are reported to release IL-17A." (PMID 34054833, 2021). "Our results suggest that nociceptive sensory neurons may drive the production of IL-23, resulting in IL-17A production from γδ T cells via the neuropeptide CGRP in the pathology of psoriasis." (PMID 34745116, 2021). "While male B6 mice did not develop arthritis despite similar serum IL-23 and IL-17A levels, other disease manifestations (weight loss, colitis, psoriasis-like skin disease, bone loss) were observed in both strains." (PMID 33983951, 2021). "Exosomes derived from human epidermal keratinocytes treated with psoriasis-related cytokines, such as IL-17A, IL-22, IFN-γ, and TNF-α, stimulate normal human neutrophils, followed by NF-κB and p38 MAPK signaling activation, leading to the production of TNF-α, IL-6, and IL-8, and NET formation." (PMID 34944704, 2021). "IL17A inhibitors are currently commonly used to treat psoriasis." (PMID 34122426, 2021). "Statins are beneficial to psoriasis treatment, possibly by inhibiting the IL-17A signaling pathway." (PMID 33762935, 2021). "In addition, an ex vivo human psoriasis skin co-culture system was used to examine the effects of biologics targeting IL-17A on IL-19 expression." (PMID 34616394, 2021). "Together, these results indicated that glycyrrhizin improved psoriasis by inhibiting the expression of IL-17A and IFN-γ in vivo and suppressed the proliferation of IL-17A-HaCaT cells and the expression of STAT3, p-STAT3, and a-STAT3 by upregulating SIRT1 in vitro." (PMID 34044769, 2021). "Moreover, CD8αα+T cells exhibited a pro‐inflammatory role in psoriasis by producing IL‐17A and IFN‐γ." (PMID 35663772, 2021). "IL-17A is important in relieving psoriasis by upregulating cytokines IL-6, IL-1β, and TNF-α." (PMID 34054833, 2021). "Indeed, neutrophil-keratinocyte crosstalk is an early target of IL-17A antibody-mediated therapies in psoriasis, suggesting that communication of keratinocytes and neutrophils is involved in the immunopathogenesis of psoriasis." (PMID 34421918, 2021). "Taken together, the animal studies showed good safety, efficacy, and preclinical PK characteristics of QX002N injection, indicating that QX002N injection is a viable candidate for clinical application as an anti-IL-17A monoclonal antibody to treat psoriasis and AS." (PMID 35310892, 2021). "Since CCL20 is a ligand for CCR6, which is a signature molecule of IL-17A-producing T cells, the activated keratinocytes in the disease-naïve sites of psoriasis are to recruit IL-17A-producing T cells to the disease-naïve sites, leading to the accumulation of IL-17A-producing TRM." (PMID 34501272, 2021). "In a study of patients with psoriasis, it is found that IL-21 up-regulates RORγt expression and down-regulates the expression of Foxp3, increases secretion of IL-17A and IL-22, and finally induces T-helper 17 (Th17) and Tregs imbalance and promotes inflammation in psoriasis." (PMID 34490267, 2021). "In summary, these data indicate that glycyrrhizin may play a therapeutic role in improving psoriasis through IL-17A and the SIRT1-STAT3 axis." (PMID 34044769, 2021).
psoriasis (continued). "For IL-9 and IL-17 a significant decline of the serum levels has been shown after 3 months of systemic MTX therapy in patients with psoriasis and furthermore IL-9 serum levels were decreased after treatment with glucocorticoids in patients with systemic lupus erythematosus." (PMID 33995403, 2021). "IL-23/IL-17A axis plays a central role in the development of psoriasis." (PMID 34992498, 2021). "These suggest systemic Th17 over-activation or systemic over-secreted IL-17A circulation may be a link between disordered gut microbiota and psoriasis development." (PMID 34881280, 2021). "Also, higher serum and lesional levels of a member of this family, IL-17A, in psoriasis patients compared to controls have been reported which supports the role of IL-17 A in this disease." (PMID 33500449, 2021). "Emerging evidence suggests an important role for IL-17F in SpA spectrum disease and psoriasis since dual suppression of IL-17A and IL-17 may offer benefit, especially in the skin." (PMID 33544244, 2021). "Nowadays, part of them is a target of biological drugs used in psoriasis therapy, e.g., IL-17A." (PMID 33467067, 2021). "However, the role of IL-17A in RA is up for debate, since therapeutic targeting of either IL-17A or the IL-17R showed lower efficacy than for example in the treatment of psoriasis." (PMID 32260219, 2020). "Monoclonal antibodies against IL-17A or IL-17RA are already available to patients affected by psoriasis and arthritis, and might even find application in malignancies." (PMID 33244315, 2020). "Moreover, psoriasis mice model has shown that the expression of IL-17A in peripheral immune cells is increased." (PMID 32987907, 2020). "Our data support the hypothesis that targeting IL-17A should result in an improvement of the EC damage observed in psoriasis patients." (PMID 32352958, 2020). "During my research on the pathogenesis of psoriasis and the therapeutic mechanisms of anti‐interleukin‐17A (anti‐IL‐17A) and anti‐interleukin‐23 (anti‐IL‐23) antibodies on psoriasis, I considered whether these antibodies would also be effective against AD." (PMID 31849180, 2020). "Since psoriasis is considered to be an IL-17A-driven disease, serum IL-17A levels were measured." (PMID 33171607, 2020). "Moreover, γδT cells have been recently reported to be a major IL-17A producer in human psoriatic lesion and mouse psoriasis-like skin inflammation." (PMID 32454795, 2020). "All three anti-IL-17A biologics exbibit remarkable therapeutic efficacy for psoriasis." (PMID 32070069, 2020). "Therefore, psoriasis is considered an excellent human model of how IL-17A works with target peripheral tissues, and it provides in-depth insight into human autoinflammatory diseases." (PMID 32070069, 2020). "Furthermore, metformin was reported to reduce IL-17A production and the population of Th17 cells, which are critical factors in the development of psoriasis, in a murine experimental autoimmune encephalomyelitis model." (PMID 32194991, 2020). "Biological DMARDs can also block T-cell-derived factors: blockade of Th17-derived IL-17A may ameliorate CVD in psoriasis, although further studies are needed." (PMID 33117403, 2020). "However, the trial was terminated by the sponsor based on the development of another anti-IL17A mAb, Ikekizumab, with better activity than Secukinumab for psoriasis and superior potential in treating MS." (PMID 32093011, 2020). "Psoriasis is one of the most typical IL-23/IL-17A-driven human diseases." (PMID 32070069, 2020). "In several studies, it has been demonstrated that IL-17A significantly enriched the mTOR pathway and mediated the proliferation of fibroblast-like synovial cells by mediating this pathway and inflammatory responses in psoriasis." (PMID 33099538, 2020). "Although TNFα-targeting and IL-17a-targeting drugs have been found to be effective, a targeting strategy that inhibits Peli1 might be a more powerful approach to treat psoriasis." (PMID 32873845, 2020).
psoriasis (continued). "Other authors observed correlations of IL-17A with psoriasis severity." (PMID 32587472, 2020). "IL-17A has been known to play an important role in the aggravation of pathology, not only in several cancers but also in autoimmune diseases such as rheumatoid arthritis, spondyloarthritis, multiple sclerosis, and psoriasis." (PMID 32059488, 2020). "One good therapy may be to use anti‐IL‐17A antibody, because this antibody can be thought to interfere with neutrophil infiltration in psoriasis." (PMID 31849180, 2020). "However, as psoriasis is an IL-17A dominated disease, we added IL-17A, IL-22, TNF-α and IFN-γ to our psoriasis-like HPKs." (PMID 32316273, 2020). "Moreover, IL-17A upregulates IL-36G production more potently in human psoriasis-derived keratinocytes than in healthy keratinocytes." (PMID 32070069, 2020). "In this review, we focus on IL-17A and keratinocyte interaction regarding psoriasis pathogenesis." (PMID 32070069, 2020). "Interestingly, two other approved therapeutics for psoriasis, broadalumab (anti-IL-17A) and etanercept (anti-TNF), also downregulate KLK-7 mirroring apremilast-induced effect, thus providing plausible explanations of converged therapeutic mechanism." (PMID 31953524, 2020). "In the present study, the increased IL-17A+γδ+T cell percentage was also found in spleen and skin lesions of psoriatic mice model, which further confirmed the important role of IL-17A+γδ+T cells in the pathogenesis of psoriasis." (PMID 32454795, 2020). "Specific immunomodulatory therapies by antibodies in humans to neutralize the IL-17A activating cytokine IL-23 or the effector cytokine IL-17A itself have been successful in the treatment of psoriasis, psoriatic arthritis, rheumatoid arthritis and ankylosing spondylitis." (PMID 32106855, 2020). "Since IL-12 can induce IFN-γ production and CD49a expression, it is tempting to speculate that in the psoriasis context, IL-17A-producing TRM cells, which preferentially express IL-23R, downregulate their CD49a due to a greater influence of IL-23 over IL-12." (PMID 33633737, 2020). "The IL-23/IL-17A-Th17 axis has a crucial role in the development of psoriasis." (PMID 32684837, 2020). "IL-17A, and its structurally similar family member IL-17F, have been shown to be functionally dysregulated in certain human immune-mediated inflammatory diseases such as psoriasis, psoriatic arthritis, and axial spondyloarthritis." (PMID 32973785, 2020). "Human psoriasis is a chronic, heterogeneous immune-mediated inflammatory disease with genetic and epigenetic triggers that activate pro-inflammatory pathways, including IL-17A." (PMID 33301461, 2020). "However, daphnetin treatment attenuated IMQ-induced upregulation of those inflammatory cytokines in IMQ-induced psoriasis-like skin lesion at a certain extent, significantly reduced the expression of IL-6, IL-23A and IL-17A." (PMID 33081840, 2020). "Therefore, we are also very interested in its role in apoptosis in psoriasis and found that IL-17A was dramatically increased in psoriatic lesions (n = 23) vs. HC (n = 12) by RT-qPCR (P < 0.05)." (PMID 32632545, 2020). "Furthermore, hBD-2 was identified as a biomarker of IL-17A-driven pathology by comparing protein expression in patients with psoriasis versus that in healthy subjects." (PMID 32947991, 2020). "BA was previously found to be able to ameliorate psoriasis-like murine skin inflammation by decreasing the number of γδ T cells and IL-17A-expressing CD4+ in psoriatic mice, and inhibiting the proliferation of T cell and IL-17A production by CD4+ T-Cells in vitro." (PMID 32842569, 2020). "So combination of in vitro and in vivo results, we may conclude that Notch-Hes1 signaling can express its effects in the pathogenesis of psoriasis by regulating IL-17A+γδ+T cells." (PMID 32454795, 2020).
psoriasis (continued). "Interleukin-17A (IL-17A), originally known as the cytotoxic T lymphocyte-associated antigen 8 (CTLA-8), is a pro-inflammatory cytokine, and has emerged as a new therapeutic target in chronic inflammatory diseases, such as psoriasis and vitiligo." (PMID 33603662, 2020). "In addition, various murine psoriasis models stress a pivotal role of the IL-23/IL-17A axis in experimental psoriasis." (PMID 32070069, 2020). "In future, we hope to address whether chrysin can reverse the inhibition of TNF-α, IL-17A, or IL-22-induced differentiation in keratinocytes in psoriasis." (PMID 32076123, 2020). "Apart from IL-17A, the other IL-17 family members (IL-17C, E, and F) may also be involved in the pathogenesis of psoriasis." (PMID 33281823, 2020). "Furthermore, brodalumab, which is a human monoclonal antibody human anti-IL17RA, a pan inhibitor of IL-17A, IL-17F, and IL-25 is currently used in the treatment of psoriasis where shows a complete clearance of moderate-to-severe psoriasis." (PMID 33574815, 2020). "IL-6 and IL-22 also play a synergistic role in development of psoriasis with IL-17A." (PMID 32070069, 2020). "Early clinical data in patients with psoriasis, in those with psoriatic arthritis, and from the Phase 2 studies in psoriasis, psoriatic arthritis, and ankylosing spondylitis, are encouraging and support the targeted approach of dual neutralization of IL-17A and IL-17F." (PMID 32973785, 2020). "Indeed, antagonistic antibodies to IL-17A or IL-17RA have shown a clinical benefit in patients with psoriasis." (PMID 31936879, 2020). "Furthermore, we employed blockade of IL-17A signaling using an anti-IL-17A neutralizing monoclonal antibody in order to compare the effect with anti-IL-6R antibody on IMQ-induced psoriasis-like dermatitis in PD-1−/− mice." (PMID 33060784, 2020). "This analysis produced a list of 9 significantly altered canonical pathways (p < 0.05 or –log p-value > 1.30) including SAPK/JNK signaling, NAD biosynthesis and salvage pathway, phototransduction pathway, VDR/RXR activation, Reelin signaling in neurons, and role of IL-17A in psoriasis." (PMID 32260415, 2020). "Moreover, the keratinocyte-specific ablation of ATG5 ameliorated imiquimod-induced skin lesions in mice accompanied by a reduction in the number of IL-17A producing cells, highlighting the role of this target in psoriasis." (PMID 32630692, 2020). "Therefore, IL-17A inhibition by the anti-IL-17A biologic results in early clinical, histopathologic, and molecular resolution of psoriasis." (PMID 32070069, 2020). "Biologics targeting IL-23 or IL-17A have shown remarkable effects in the treatment of psoriasis." (PMID 33281823, 2020). "Many studies have suggested that IL-17A is involved in the pathophysiological process of multiple diseases, including inflammatory bowel disease, breast cancer, lung cancer, cardiovascular system, uveitis, rheumatoid arthritis (RA), and psoriasis." (PMID 33613566, 2020). "Subcutaneous injection of IL‐23, together with IL‐12 and TNF produced by LCs and DCs, activates αβT and γδT cells to produce IL‐22 and IL‐17A/F, which stimulate keratinocyte proliferation, release S100 protein and β‐defensin, and promote the production of growth factors and chemokines in psoriasis." (PMID 32916775, 2020). "However, different cytokines, especially IL-17A and F, highly abundant in psoriasis, strongly induced expression of S100-alarmins preferentially during early maturation stages of keratinocytes." (PMID 33643287, 2020). "To date, IL-17A blockade shows therapeutic effects on several autoimmune diseases, including psoriasis, RA, psoriatic arthritis, and ankylosing spondylitis; however, development of therapeutic treatment for SLE is very challenging because of disease complexity and heterogeneity." (PMID 31318609, 2019).
psoriasis (continued). "Because of the prevalent and conserved function of IκBζ in both IL-17A and IL-36 signaling, targeting of IκBζ expression or function in keratinocytes might become an attractive strategy for an effective long-term psoriasis therapy." (PMID 31622280, 2019). "Meanwhile, the mice exhibited higher serum levels of psoriasis mediators, such as interleukin-22 (IL-22), IL-17A and its downstream molecule regenerating islet-derived 3γ (Reg3γ), which has been confirmed to be a critical molecule in psoriatic epidermal hyperplasia." (PMID 31521168, 2019). "Indeed several cytokine-targeted therapies, including those targeting the IL-1 and IL-17A pathways, are used clinically to treat conditions such as RA, MS and psoriasis." (PMID 31231388, 2019). "In agreement, neutralizing antibodies against IL-17A and IL-23 represent effective state-of-the-art therapies for the treatment of patients with psoriasis, whereas antagonizing IL-36 receptor antibodies are currently being investigated as a new therapy approach for psoriasis." (PMID 31622280, 2019). "The resulting ischemic diseases (e.g., myocardial infarction, cardiomyopathies or stroke) represent a prognosis-relevant comorbidity frequently associated with most inflammatory conditions, including those, like psoriasis, in which IL-17A appears to play an important role." (PMID 32010143, 2019). "Psoriasis constitutes a common autoinflammatory disease of the skin, which is characterized by keratinocyte hyperproliferation as well as massive infiltration of neutrophils, macrophages, and IL-17A–expressing T cells." (PMID 31622280, 2019). "Keratinocyte-specific depletion of IκBζ prevents IL-17A–dependent psoriasis." (PMID 31622280, 2019). "In an animal experiment, it is observed in the imiquimod-induced psoriasis-like mice that the epidermal expression of IL-23, IL-17A, and IL-17F is increased, whereas disease development was almost completely blocked in mice deficient for IL-23 or the IL-17 receptor." (PMID 31583255, 2019). "In addition, IL-17A is postulated to lead to increased anti-microbial production from epithelial cells, which is lower in AD compared with psoriasis (Uluçkan and Wagner, 2017)." (PMID 31644908, 2019). "Interestingly, we now show that depletion of IκBζ in keratinocytes is sufficient to protect against psoriasis, although these K14-KO mice still display elevated numbers of infiltrating T cells and increased Il17a expression in the skin." (PMID 31622280, 2019). "IL-17A is now a registered target in psoriasis, psoriatic arthritis, ankylosing spondylitis." (PMID 31396230, 2019). "We hypothesized that if a significant amount of IL-17A and IL-22 is produced by IL-17A/IL-22 dual secreting Th17 cells in psoriasis, then the gene expression of these two cytokines should correlate with one another." (PMID 31019502, 2019). "In sum, psoriasis and vascular disease appear to (at least partially) share common pathogenetic mechanisms, and an anti-inflammatory therapy (with a focus on the IL-17A signaling cascade) appears to not only reduce the skin manifestations, but also to improve (cardio)vascular function." (PMID 32010143, 2019). "In psoriasis, IL-17A secreted from type 17 helper T cells has a pivotal role in pathogenesis." (PMID 31831764, 2019). "In addition to IL-6, a transient increase in IL-23 followed by IL-17A production was observed in the IMQ-induced psoriasis model." (PMID 31659208, 2019). "Similarly, mannan from Saccharomyces cerevisiae (Baker’s yeast) administered by intraperitoneal injection to mice induces a PsA-like disease with joint inflammation and psoriasis-like skin lesions, which are prevented by neutralization of IL-17A." (PMID 31447673, 2019). "Herein, we conduct meta-analyses of RNA-seq datasets to directly evaluate the current hypothesis that dual-secreting IL-17A/IL-22 Th17 cells are the dominant effector population in psoriasis." (PMID 31019502, 2019).